HIF1A (hypoxia inducible factor 1 subunit alpha)
Diseases named in the same sentence as HIF1A in open-access papers (continued):
Sharing a sentence is not in itself a finding about the gene and the disease.
prostate carcinoma (continued). "The findings of the current study suggested that NANOG expression may be a biomarker for the diagnosis of prostate cancer, and the coexpression of NANOG and HIF-1α may be involved in prostate carcinogenesis." (PMID 25120646, 2014). "To investigate whether HIF-1α and VEGF are involved in berberine mediated radiosensitivity of prostatic cancer cells, we performed Western blot and immunofuorescence analysis to detect the protein expression of HIF-1α and VEGF." (PMID 24886405, 2014). "Furthermore, interfering with the hypoxia-induced accumulation of HIF-1α and ADAM10 has been shown to enhance MICA surface expression and to reduce MICA shedding, leading to augmented cytotoxicity of PBL against DU145 prostate cancer cells under hypoxia." (PMID 23724099, 2013). "Hypoxia and the consequential angiogenesis may play a major role in prostate cancer progression, as VEGF and HIF1α is increased in prostate cancer, when compared to benign prostatic hypertrophy." (PMID 22546016, 2012). "HIF1α mRNA gene expression was significantly unregulated in blood samples of localized prostate cancer patients, when compared to individuals with no malignancies or those with more advanced tumors in a recent prospective study." (PMID 22546016, 2012). "In summary, HIF1α and VEGF-A was frequently expressed in prostate cancer cells." (PMID 22546016, 2012). "Hypoxia induces HIF-1α expression in an AMPK-independent manner in mouse embryonic fibroblasts, whereas enhanced AMPK activity is important for HIF-1α transcriptional activity under hypoxic conditions in prostate cancer cell lines." (PMID 22762146, 2012). "Noteworthy, HIF1α was not prognostic in prostate cancer patients included in a French dose escalation study and an US prostatectomy series using IHC and gene expression, respectively." (PMID 22546016, 2012). "In both pancreatic and prostate carcinoma cell lines, it was shown that artificial hypoxia (by cobalt chloride)-induced VEGF expression required Src activation and resulted in increased steady-state levels of HIF-1α and increased phosphorylation of STAT3." (PMID 22988500, 2012). "The responsiveness of CTGF on activation of HIF-1α, which was described in previous studies, might be a link to an enhanced angiogenesis as it was found for CTGF in prostate cancer tumourigenesis." (PMID 21673687, 2011). "The frequency of HIF1α isoforms in benign prostate hyperplasia and prostate cancer with and without NE." (PMID 20663134, 2010). "The findings that Siah controls levels and activity of HIF-1α, which cooperates transcriptionally with FoxA2 to promote NE tumor development or formation of NED of human prostate cancers, provide a rationale for targeting the Siah/HIF/FoxA2 axis as a new therapeutic modality." (PMID 21037926, 2010). "DCPA can inhibit prostate cancer cell migration, proliferation, and HIF-1α expression, suggesting that DCPA could be potentially used for therapeutic purpose for prostate cancer in the future." (PMID 16884534, 2006). "Prostate cancer progression also depends on its ability to form new blood vessels, and calcitriol inhibits angiogenesis by reducing the expression of pro-angiogenic factors such as VEGF (vascular endothelial growth factor) and HIF-1α (hypoxia-inducible factor 1-alpha)." (PMID 40362574, 2025). "In prostate cancer studies, canagliflozin showed inhibition of the activity of mitochondrial complex I, leading to the activation of AMPK and followed by the inhibition of mechanistic target of rapamycin complex 1 (mTORC1) and hypoxia-inducible factor 1-alpha (HIF-1α) pathways." (PMID 41471707, 2025). "Moreover, a key modulator of the transcriptional response to hypoxic stress, HIF1α can also undergo Kla when lactate imported into prostate cancer (PCa) cells via MCT1, which can stabilize HIF1α under normal hypoxic conditions, enhance KIAA1199 transcription and promote angiogenesis in PCa." (PMID 38317138, 2024).
prostate carcinoma (continued). "Similarly, the acute exposure to arsenite has been found to activate PI3K and AKT signaling, which regulates hypoxia inducible factor 1 subunit alpha (HIF-1) and vascular endothelial growth factor (VEGF) expression by generating reactive oxygen species (ROS) in prostate cancer cells." (PMID 35954277, 2022). "Furthermore, hypoxia inducible factor-1α (HIF-1α) and its downstream target genes, such as VEGF, could regulate the cell response to hypoxia, and might confer resistance to radiotherapy of prostate cancer." (PMID 35889396, 2022). "It has been shown that bortezomib inhibits HIF-1α transcriptional activity and attenuates its protein synthesis and the expression of its nuclear targets such as VEGF by inhibiting the PI3K/Akt/mTOR and MAPK pathways in AD and AI prostate cancer (PCa) cells, respectively." (PMID 36139386, 2022). "The authors suggested that there might not be any correlation between hypoxia and HIF-1α in prostate cancer, but they could not explain the absence of [18F]-FAZA-PET visualization." (PMID 34073301, 2021). "Besides the direct regulation by HIF-1α and SMAD3, through some other public ChIP-Sequencing dataset, we also found that, in PCa, CDCA2 was a directly regulated by MEN1, which function as an oncogene in prostate cancer (GEO: GSE132827)." (PMID 32509575, 2020). "We have shown that the splice variants of ERβ, the ERβ2 and ERβ5 isoforms, interact with HIF-1α and HIF-2α while we could not detect any HIF interaction with ERβ1 (the wt form) in prostate cancer cells." (PMID 32413024, 2020). "Additionally, modulation of the angiogenic pathway was observed in prostate cancer cells following treatment with DD1E5: the pro-angiogenic factors VEGF, iNOS, c-Myc, and HIF-1α were all downregulated, indicating that DDAH1 inhibition attenuates the angiogenic potential of DDAH1+ cells." (PMID 31993367, 2019). "siRNA-mediated knockdown of HIF-1α or HIF-2α selectively decreased expression of the respective protein in the three pancreatic cancer cell lines MiaPaca-2, SW1990, and Panc10.05; in the prostate cancer cell line DU145; and in the cervical cancer cell line HeLa." (PMID 28476028, 2017). "To confirm whether pristimerin suppresses hypoxia-induced HIF-1α accumulation via the inhibition of SPHK-1 and ROS generation in prostate cancer cells, we evaluated the effect of NAC on HIF-1α and SPHK-1 abundance in hypoxic PC-3 cells, treated with pristimerin." (PMID 27581969, 2016). "Here we show for the first time that in prostate cancer cells mTORC1 increases SK1 expression through HIF-1α in normoxic conditions, a pathway that may be interrupted by mTOR inhibitor RAD001." (PMID 27821815, 2016). "However, our results showed that KLF5 did not alter the transcription of HIF1α either in mouse prostates or in human prostate cancer cells." (PMID 25896712, 2015). "It is known that HIF1α could induce the expression of PHD331, but the expression of PHD2 and FIH1 under hypoxic condition is very complicated in different cell lines, especially in prostate cancer cells." (PMID 26205124, 2015). "It is noteworthy that the previous studies in human prostate cancer cells have shown that selenium can inhibit as well as activate AKT 51; however, our data unequivocally show that MSeA activates the AKT protein kinase (at early time point) concurrent with reduction in HIF-1α expression." (PMID 24515947, 2014). "In PC-3 ML human prostate cancer cells and in HCT116 human colon carcinoma cells, it was demonstrated that PGE2 and hypoxia act both independently and synergistically to increase HIF-1α protein levels, and further demonstrated the time-dependent nuclear accumulation of HIF-1α in response to PGE2." (PMID 23566437, 2013). "In addition to hypoxia, HIF-1α expression is also induced under normoxic conditions as HIF-1α levels were up-regulated in the prostate cancer cell line PC3 but not LNCaP." (PMID 23844087, 2013).
prostate carcinoma (continued). "Here we investigated the expression of miR199b and HIF-1α in normal prostate tissue, prostate cancer tissues and prostate carcinoma (PCa) cell lines LNCaP, PC-3 and DU145.We found that miR-199b expression level was decreased in prostate cancer while HIF-1α was significantly over-expressed." (PMID 23594994, 2013). "Based on the sequences published by the National Center for Biotechnology Information (NCBI), we designed primers to amplify known HIF1α isoforms and determined their presence in benign prostate hyperplasia and prostate cancer with and without NE differentiation." (PMID 20663134, 2010). "Moreover, both HIF-1α and HIF-2α cooperate in the activation of a prognostic transcriptional pattern delineating an aggressive tumor in the human prostate cancer model that we used in this study, rendering both molecules interesting targets for anticancer intervention and zinc a valid tool." (PMID 21179202, 2010). "Interestingly, other cells (including MCF-7, HT-29 colon, MiaPaCa pancreatic, A549 lung, and BX-PC3 prostate cancer cells) do not show measurable HIF-1α levels under normoxia." (PMID 19347037, 2009). "Thus, this V-ATPase-HIF-1α pathway is not specific to prostate cancer." (PMID 29988966, 2018). "It should also be taken into account that HIF-1α/SEPT9_i1 complex (BiFC signal) could be influenced by other cellular functions, such as the androgen-androgen receptor pathway, which does not exist in PC-3 prostate cancer cells." (PMID 28380438, 2017). "Based on our finding that manipulation of KLF5 expression in human prostate cancer cells affected tube formation and migration of HuVECs, we further tested whether manipulation of KLF5 expression also affects the expression of HIF1α and other pro-angiogenic factors as in mouse tissues." (PMID 25896712, 2015). "Therefore, targeting HIF-1α expression through ILK inhibition, in combination with androgen deprivation therapy, may be a rational therapeutic strategy to prevent or delay progression to castration-resistant prostate cancer." (PMID 25821081, 2015). "Using the Cancer Genome Atlas (TCGA) dataset, we observed that high expression of CTBP2 was significantly correlated with poor overall survival of prostate cancer patients, while AKAP12, HIF1A and RHOB were not." (PMID 38698344, 2024). "The concomitant expression of PLGF, HIF-1α, and VEGFR1 (FLT1 gene) was significantly higher in metastasis compared to non-metastatic prostate cancers (p = 1.71 × 10−1)." (PMID 39457506, 2024). "Results show that similar to prostate cancer, in mouse GCs, DHT stimulation does not affect Hif1α mRNA levels but increases HIF1α protein levels." (PMID 33784295, 2021). "Although upregulation of HIF-1α has been shown to promote prostate adenocarcinoma (PCa) progression, the mechanism by which miRNAs modulate HIF-1α in prostate cancer has not been clarified." (PMID 29137361, 2017). "We studied the HIF1α isoforms present in 8 cases of benign prostate hyperplasia (BPH) and 43 cases of prostate cancer with and without NE differentiation using RT-PCR, sequencing analysis, immunohistochemistry and in situ hybridization." (PMID 20663134, 2010). "It was found that HIF-1α but not HIF-2α (EPAS1) depletion in BM macrophages reduced the expression of the pro-tumorigenic inflammatory cytokines Mif and Cxcl4 after being exposed to apoptotic prostate cancer cells when compared to WT BM macrophages." (PMID 36496973, 2022). "In DU145 human prostate cancer cells, PRKAA1 activity is required for HIF1A transcriptional activity and expression of HIF1A-targeted genes, but this does not occur through the modulation of HIF1A protein expression, stabilization, or nuclear translocation." (PMID 30405100, 2018).
prostate carcinoma (continued). "Our data indicate that in prostate cancer cells 5 nM docetaxel does not inhibit mTORC1 activity (as assessed by p-P70S6K), HIF-1α protein levels, SK1 activity and expression and that combining docetaxel with RAD001 allows a marked reduction in these signaling pathways and chemosensitization." (PMID 27821815, 2016). "Therefore, despite functional SNPs in genes of pathways downstream of HIF-1α, such as KDR, LOX and CAIX, have not been studied so far in prostate carcinoma patients, they merit further research as they represent key molecules in hypoxia-generated stimulus in cancer." (PMID 28143503, 2017).
pancreatic cancer (425 papers, 2002 to 2026). "More precisely, we identified distinct miRNA199 subtypes (199a/b-3p, 199a-5p), and it has previously been described that polymorphisms in the miRNA199 target site within the HIF-1α mRNA sequence are linked to an increased pancreatic carcinoma risk." (PMID 41602419, 2026). "Collectively, MYB, its crosstalk with HIF1α, and their coregulated downstream target genes represent attractive targets for therapy and potential biomarkers for risk prediction in pancreatic cancer." (PMID 40680814, 2025). "Overexpression of HIF-1α is linked to gemcitabine-resistant pancreatic cancer cells, and its inhibition has been shown to partially reverse epithelial-to-mesenchymal transition (EMT), a process critical to metastasis and drug resistance." (PMID 39458615, 2024). "In pancreatic tumors, the hypoxic microenvironment stabilizes HIF-1α, the master regulator of glucose metabolism, and causes glucose dependency in cancer cells." (PMID 38540735, 2024). "Intratumoral hypoxia is associated with the invasion and metastasis of HIF-1α-active pancreatic cancer cells, and eradication of the HIF-1α-active cells compromises malignant progression." (PMID 37490147, 2023). "HIF-1α overexpression has been associated with the formation of metastatic tumors with a poor prognosis for patients with pancreatic cancer." (PMID 37626752, 2023). "For example, HIF-1α has been widely studied in many cancers, including pancreatic cancer, and overexpression of HIF-1α is significantly associated with poor prognosis in pancreatic cancer." (PMID 35789607, 2022). "HIF-1α is a major regulator of glycolysis and overexpressed HIF-1α is associated with chemoresistance in pancreatic cancer." (PMID 35898887, 2022). "Several studies have confirmed that HIF-1α meets the metabolic needs of pancreatic cancer cells by increasing the expression of glycolysis-associated enzymes and the production of lactate." (PMID 36408139, 2022). "HIF-1α, as a principal regulatory response to hypoxia tolerance, has been shown to mediate genes associated with pancreatic cancer progression, prognosis, and surgical outcomes." (PMID 33830713, 2021). "This sponging effect causes the HIF1α-induced immune escape of pancreatic cancer cells through the mechanism of targeting HIF1α/ADAM10." (PMID 34162394, 2021). "HIF-1α is commonly overexpressed in pancreatic cancer, and it is further linked to greater cancer invasion and metastasis." (PMID 34207699, 2021). "YTHDC2 has been identified as a frequently mutated gene in pancreatic cancer patients and plays a role in tumor metastasis by increasing the translational efficiency of HIF-1α." (PMID 32547941, 2020). "In conclusion, salidroside was a novel therapeutic drug in pancreatic cancer, and downregulation of HIF‐1α and LXCL2 was the underlying mechanism." (PMID 31162697, 2020). "For another important zinc-finger binding transcription factor Slug, HIF-1α was associated with its expression in head and neck squamous carcinoma, lung, and pancreatic cancer cells." (PMID 32322559, 2020). "Metastasis-associated protein 2 (MTA2) stabilizes the HIF-1α protein via deacetylation in pancreatic cancer, and its transcriptional regulator RNA MTA2TR is transcriptionally regulated by HIF-1α under hypoxic conditions." (PMID 32550915, 2020). "Western blot analysis of the expression of EMT-associated proteins and HIF-1α/SDF-1/CXCR4 of pancreatic cancer tissues revealed that bufalin significantly downregulated vimentin but upregulated E-cadherin in PANC-1 cells." (PMID 32362830, 2020). "The expression of HIF-1α is also linked with pancreatic cancer progression, angiogenesis, EMT and metastasis." (PMID 30455857, 2018). "In this study, we demonstrate that the genetic variants of rs2057482, a SNP located within the 3′ UTR of HIF1A, can weaken the suppression of HIF1A by miR-199a and is associated with the risk of pancreatic cancer and shorter survival of patients with PDAC." (PMID 26872370, 2016).